TNF (tumor necrosis factor)
Diseases named in the same sentence as TNF in open-access papers (continued):
Sharing a sentence is not in itself a finding about the gene and the disease.
thyroid cancer (59 papers, 2010 to 2025). "Our results indicated a suggestive association between thyroid cancer and decreased circulating levels of TNF and IFN-γ, as well as a suggestive association with increased circulating levels of LIFR." (PMID 40072746, 2025). "Clinical data indicate that serum TNF-α levels are significantly elevated in thyroid carcinoma patients and are associated with tumor staging." (PMID 40823082, 2025). "Limited studies evaluate thyroid function tests in Ax-SpA patients on TNF-alpha inhibitors, and only a few studies analyze the effect of TNF-alpha inhibitor use on thyroid nodules and its association with thyroid cancer." (PMID 39630724, 2024). "Based on current evidence, our meta-analysis suggests that TNF-α exhibit a strong association with thyroid carcinoma." (PMID 32819324, 2020). "In summary, our meta-analysis suggests that adipokines, including TNF-α, IL-6 and leptin are associated with thyroid carcinoma." (PMID 32819324, 2020). "The results of the present study show that the selective BRAF-inhibitor, PLX4720, inhibits the basal and the TNFα-stimulated secretion of CXCL8 in BRAFV600E mutated thyroid cancer cell lines (BCPAP, 8305C and 8505C)." (PMID 30867499, 2019). "Collectively, the present results reflect that TNF-α could be used as a prognostic and diagnostic marker of Hashimoto’s disease in patients with thyroid cancer." (PMID 35203561, 2022). "Thus, the current findings suggest that TNF-α could be used as an indicator of thyroid cancer risk from benign conditions and may have a role in development of tumour and prognosis of thyroid cancer patients." (PMID 26881177, 2016). "We have further evaluated the IL-6 and TNF-α cytokine release in the culture supernatants of 48 h drug-treated K1 thyroid cancer cells." (PMID 41150811, 2025). "IL-17 and TNF-α are potential prognostic markers for patients with Hashimoto's disease complicated by thyroid cancer." (PMID 40892159, 2025). "Chronic inflammation enhances thyroid cancer progression, with TNF‐α and IL‐1β known to promote tumor invasiveness and survival." (PMID 41477125, 2025). "Tumor necrosis factor-α (TNF-α) is highly expressed in the thyroid carcinoma microenvironment and enhances cancer cell invasiveness by regulating pathways such as matrix metalloproteinases (MMPs)." (PMID 40823082, 2025). "In the SCM group, the TNF signaling pathway, viral protein interaction with cytokine and cytokine receptors, thyroid cancer, and African trypanosomiasis were significantly enriched." (PMID 38291374, 2024). "Our study shows that TCF19 regulates many inflammatory pathways in thyroid cancer, such as the TNF signalling pathway and IL-17 signalling pathway." (PMID 38579171, 2024). "Nevertheless, the most significant expression of TNF (tumor necrosis factor) was observed in adrenocortical tumors and thyroid carcinomas in ACME HS and nuclei samples." (PMID 39839668, 2024). "The present data also reveal that the determination of Bax, Bcl-2, IL-8 and TNF-α levels might possess a potential prognostic and diagnostic value in thyroid cancer patients, reflecting that apoptosis and inflammation are important mechanisms in thyroid cancer." (PMID 35203561, 2022). "After the thyroid cancer cells were treated with TNF-α, the expression of Twist mRNA was up-regulated and then the expression of E-cadherin was down-regulated." (PMID 34930256, 2021). "Paclitaxel prodrug-loaded TNF-α conjugated gold nanomedicine improved the drug delivery in metastatic thyroid cancers and pancreatic neuroendocrine cancers." (PMID 34944814, 2021). "The two increased miRNAs increased in several pathways, including the TNF signaling pathway, thyroid cancer, terpenoid backbone biosynthesis, signaling pathways regulating pluripotency of stem cells, and shigellosis, by pathway enrichment analysis." (PMID 32076458, 2020). "In previous studies, the analysis of adiponectin and thyroid cancer mostly focused on TNF-, IL-6, Leptin and Adiponectin." (PMID 32819324, 2020).
thyroid cancer (continued). "Twelve studies reported the expression of TNF-α both in patients with thyroid carcinoma and control subjects." (PMID 32819324, 2020). "The pooled OR with fixed-effect model of the ratio of TNF-α immunoreactivity in thyroid carcinoma tissues is 7.67 (95% CI 4.11 to 14.31, P < 0.00001)." (PMID 32819324, 2020). "Adipokines (TNF-α, IL-6 and leptin) show a strong relationship between elevated concentrations (in serum and/or tissue) and thyroid carcinoma." (PMID 32819324, 2020). "Aim of this study was to test the effect of the BRAF-inhibitor (PLX4720) on the basal and TNF-α-induced CXCL8 secretions in BRAFV600E mutated (BCPAP, 8305C, 8505C), in RET/PTC rearranged (TPC-1) thyroid-cancer-cell-lines and in normal-human-thyrocytes (NHT)." (PMID 30867499, 2019). "Incubation of mast cells with thyroid cancer cell-derived conditioned medium produced a strong upregulation of a set of selected cytokines (TNF-α, CXCL6, and CXCL8), which consistently induced EMT in thyroid cancer cells." (PMID 29977225, 2018). "Recently, several studies suggested IL-8, TGF-α and TNF-α as interesting biomarkers of thyroid cancer." (PMID 30174788, 2018). "Recently, wedescribed a similar NF-κB-dependent co-regulation of QPCT and CCL2 inepithelial cells of thyroid carcinomas upon TNF-α/IL-1β treatment." (PMID 28739588, 2017). "To investigate if NF-κB was involved in the regulation of TBX15 expression we stimulated HeLa cells and three thyroid cancer cell lines with TNF-α to activate NF-κB, and subsequently we measured the TBX15 mRNA levels." (PMID 27327083, 2016). "We demonstrate that inhibition of NF-κB decreases thyroid cancer cell proliferation and invasion, while promoting TNFα-induced apoptosis." (PMID 20492683, 2010). "We therefore predicted that inhibition of TNFα-induced nuclear translocation of p65 would sensitize thyroid cancer cell lines to TNFα-induced apoptosis." (PMID 20492683, 2010). "Here, we show distinct roles for NF-κB signaling in the regulation of thyroid cancer cell proliferation, resistance to TNFα-induced apoptosis, and invasion." (PMID 20492683, 2010). "Tumor-related leukocytosis caused by the release of cytokines such as granulocyte colony-stimulating factor (g-csf), granulocyte-macrophage colony-stimulating factor (gm-CSF), IL-1a,b, IL-3, IL-6, and TNF-α and its prognostic effect have been described in various cancers, including thyroid cancers." (PMID 40004836, 2025). "When confronted with TGF-β and TNF-α, thyroid cancer cells respond differently." (PMID 40490818, 2025). "Previous clinical studies have suggested that IL-1β, IL-2, IL-27, and tumour necrosis factor (TNF)-α could serve as biomarkers for the diagnosis and monitoring of thyroid cancer progression." (PMID 40892159, 2025). "TNF-α also exhibits cytostatic effects and acts as a growth inhibitor for thyroid carcinoma cells." (PMID 40823082, 2025). "Subsequent Kyoto Encyclopedia of Genes and Genomes analysis suggested that these genes may be involved in thyroid cancer, NF-κB signaling pathway, transcriptional misregulation in cancer, IL-17 signaling pathway, and TNF signaling pathway." (PMID 37792772, 2023). "Furthermore, the determination of Bax, Bcl-2, IL-8 and TNF-α levels constitute a major important marker for investigation of the mechanisms of apoptosis and inflammation in thyroid cancer." (PMID 35203561, 2022). "The study also investigated the potential apoptotic and inflammatory mechanisms involved in thyroid cancer through the determination of B-cell lymphoma 2 (Bcl-2), interleukin-8 (IL-8) and tumor necrosis factor α (TNFα) during the different stages of the cancer using a series of molecular methods." (PMID 35203561, 2022). "In addition, high levels of serum tumor necrosis factor-alpha (TNF-α), interleukin-6, TNF-α immunoreactivity, and leptin hormone in thyroid tissues have been demonstrated in patients with thyroid cancer." (PMID 36230635, 2022).
thyroid cancer (continued). "TNF-α has the ability to promote the production of granulocyte-colony stimulating factor by thyroid fibroblasts, which may play an important role in thyroid cancer." (PMID 32819324, 2020). "Pathway enrichment analysis showed that several pathways, including TNF signaling pathway, thyroid cancer, terpenoid backbone biosynthesis, signaling pathways regulating pluripotency of stem cells, and shigellosis, were mostly related to the two significantly increased miRNAs." (PMID 32076458, 2020). "A previous study suggests that HO-1 stimulated by hemin or cadmium may protect thyroid cancer cells from tumor necrosis factor-α and cycloheximide-induced apoptosis." (PMID 30149527, 2018). "Developing preventive and therapeutic strategies targeted towards TNF-α may help induce antitumour immunity, further reducing the rates of recurrence and mortality in thyroid cancer." (PMID 26881177, 2016). "Of importance, we found that TBX15 mRNA expression was increased in response to TNF-α in HeLa and three thyroid cancer cell lines; moreover, the analysis of the TBX15 expression in p65-/- MEF cells stimulated with TNF-α indicated that the effect was mediated by NF-κB." (PMID 27327083, 2016). "Furthermore, we found that LDOC1 expression sensitizes thyroid cancer cells to apoptosis by suppressing both basal and TNFα-induced activation of NF-κB signaling, and, consequently, increases the responsiveness of these cells to TGF-β1 inhibitory signaling." (PMID 26637328, 2015). "Furthermore, activated BRAF promotes cell survival by inducing the expression or the phosphorylation of BCL-2 family members and suppresses apoptotic responses against staurosporine and TNFα/cycloheximide in thyroid carcinoma cells." (PMID 26084290, 2015). "Additionally, the downregulation of circulating TNF levels may participate in the downstream processes of thyroid cancer." (PMID 40072746, 2025). "However, the molecular mechanisms underlying TNF-α-increased invasion of thyroid cancer are still not fully understood." (PMID 33854637, 2021). "Thus, inhibition of UHRF1 contribute to suppression of cytokines transcription (IL-8, TGF-α and TNF-α), which might relieve the inflammatory reaction in advanced thyroid cancer patients." (PMID 30174788, 2018). "Overall the results signify that the interaction between TNF-α and the adhesion molecules may have a role in thyroid carcinogenesis and understanding this complexity may offer potential therapeutic targets for better management of thyroid cancer." (PMID 26881177, 2016). "Research in thyroid cancer has revealed that Th1 lymphocytes can stimulate production of interferon-gamma (IFN-γ) and tumor necrosis factor-alpha (TNF-α), leading to release of CXCL10 and CXCL8." (PMID 40313970, 2025). "In thyroid cancer cells, three putative NF-κB matching sites were found in a 600-bp segment of TBX15's 5'flanking region, in response to the ectopic expression of TNF-α or NF-κBp656." (PMID 37328486, 2023). "It is well known that the tumor necrosis factor alpha (TNF-α) receptors, folate receptor (FA), and thyroid-stimulating hormone receptor are highly expressed in thyroid cancer." (PMID 34944814, 2021). "Leptin can increase the expression of VEGF, interleukin-6 (IL-6), and tumor necrosis factor-α (TNF-α) to promote progression and metastasis of thyroid cancer." (PMID 33194342, 2020). "It has been found that undifferentiated thyroid cancer originated cell lines secreted high levels of IL-6, TGF-α and TNF-α." (PMID 30174788, 2018). "Aim of this study was to test the effect of IFNγ on the basal and TNFα-stimulated secretion of CXCL8 in TCP-1 and BCPAP thyroid cancer cell lines (harboring RET/PTC rearrangement and BRAF V600e mutation, resp)." (PMID 27555670, 2016). "Additionally, PANoptosis participates in thyroid cancer immune evasion by modulating macrophages, CD4+T cells, activated T cells, B cells, and TNF signaling pathways." (PMID 41430255, 2025).
thyroid cancer (continued). "Our study suggests that PANoptosis may be involved in immune dysregulation in thyroid cancer by regulating macrophages, CD4+ T cells and activated T and B cells and TNF signalling pathways." (PMID 39104814, 2024). "Such a regulated expression of QC, but not isoQC, was already reported for thyroid carcinomas and for Human Umbilical Vein Endothelial Cells (HUVECs) after stimulation with TNF-α/IL-1β." (PMID 39272984, 2024). "In conclusion, level of serum TNF-α and the ratio of TNF-α immunoreactivity in tissues of thyroid carcinoma patients are significantly higher than control subjects which are without thyroid carcinoma." (PMID 32819324, 2020). "At variance with these results, metformin did not affect the TNF-α-stimulated secretion of CXCL8 in thyroid cancer cell lines harboring the RET/PTC rearrangement or the BRAF V600e mutation (TPC-1 and BCPAP cells, resp)." (PMID 27555670, 2016). "Aim of the present study was thus to investigate whether IFNγ inhibits the basal and the TNF-α-stimulated secretion of CXCL8 in TCP-1 and BCPAP thyroid cancer cells." (PMID 27555670, 2016). "When paired with other inflammatory agents, continuous TNF-α exposure induces tumor cells to multiply and grow through angiogenesis, which can lead to EMT in human cancer cell lines, CXCR2 and CXCR3 expression in renal cell cancer cell lines, and IFN-γ and TNF-α expression in thyroid cancer." (PMID 37598126, 2023). "This is because on the one hand, it could secrete histamine, CXCL1/GRO-α and CXCL10/IP-10 to promote the proliferation of thyroid cancer cells, and on the other hand, it could initiate EMT by secreting TNF, IL-6 and CXCL8/IL-8, which were essential in EMT process." (PMID 36568979, 2022). "It was reported that the inactivation of AMPK prompted the growth and development of thyroid tumors, and the AMPK-activator (AICAR) could inhibit the basal and the TNF α-induced CXCL8 secretion, both in normal human thyroid cells and in thyroid cancer cell lines." (PMID 32733803, 2020). "Furthermore, a recent study reported that MTF could inhibit the secretion of CXCL8 stimulated by tumor necrosis factor-α (TNF-α) in primary cultures of normal thyroid cells and differentiated thyroid cancer cells." (PMID 31379740, 2019). "The present study demonstrates that IFNγ inhibits the basal and TNFα-stimulated secretion of CXCL8 in BCPAP, but not in TPC-1 thyroid cancer cell lines." (PMID 27555670, 2016). "Similarly, designed studies showed that IFN-γ does reduce the basal and the TNFα-stimulated secretion of CXCL8 both in normal thyroid cells and in BCPAP cells, but not in the TPC-1 thyroid cancer cell line." (PMID 29977225, 2018).
triple-negative breast carcinoma (59 papers, 2012 to 2025). An invasive breast carcinoma which is negative for expression of estrogen receptor (ER), progesterone receptor (PR), and human epidermal growth factor receptor 2 (HER2). "In triple-negative breast cancer, upregulation of the pro-inflammatory cytokine TNFα has been shown to be associated a more aggressive cancer type, via the activation of genes involved in invasion." (PMID 38139316, 2023). "TNF-α rs1800629 was found to be positively associated with distant metastases of triple negative breast cancer patients." (PMID 28881857, 2017). "Interestingly, triple negative breast cancer (TNBC) patients with TNF-α-308A had an increased risk of distant tumour metastasis (OR = 3.80, 95% CI: 1.31–11.02, P = 0.009)." (PMID 26165253, 2015). "siRNA-mediated knockdown of the inflammatory cytokine tumour necrosis factor-alpha (TNF-α) presents a novel therapy for triple-negative breast cancer (TNBC)." (PMID 41439881, 2025). "In conclusion, ATM knockdown upregulates HLA expression in triple-negative breast cancer through activation of the c-Jun/TNF-α/p-STAT1 signaling pathway." (PMID 40825766, 2025). "Nuclear Factor-κB Interacting LncRNA (NKILA) is an inflammation-induced LncRNA molecule that has been recognized in triple-negative breast cancer cells after exposing them to tumor necrosis factor (TNF)-α and interleukin-1β (IL-1β)." (PMID 36770654, 2023). "This is accompanied by the induction of the tyrosine-protein kinase JAK (JAK-STAT) pathway and tumor necrosis factor α (TNF-α) signaling in triple-negative breast cancer patients and can lead to up-regulation of PD-L1 in cancer cells." (PMID 36831326, 2023). "Taking into account TNF-α expression as an important factor in antitumoral response, a clinical study on triple-negative breast cancer (TNBC) used TNF-α expression profiles as a biomarker to evaluate patients’ response to LCL161 and paclitaxel." (PMID 35406442, 2022). "In this study, we investigated the effect of TNFα on primary triple-negative breast cancer (TNBC) stem cells to understand the role of TNFα in vascular attraction in the tumor-microenvironment and pre-metastatic niche formation in the liver." (PMID 36290384, 2022). "On the other hand, an interesting thing was found in triple-negative breast cancer with a specific gene signature characterized by positive expression of TNF-α." (PMID 35406442, 2022). "Depending on the functional assay, Ki16425 inhibited the LPA-induced stimulation in triple-negative breast cancer and luminal A cell lines in a variable intensity and enhanced secretion of IL-8, IL-6 and TNF-alpha in MDA-MB-468 cells." (PMID 35365723, 2022). "In this study, we demonstrate TNFα effects on primary triple-negative breast cancer stem cells (BCSCs)." (PMID 36290384, 2022). "Biomarkers identifying which tumor types are likely to show success with Smac mimetics are limited although a recent publication suggests in triple negative breast cancer tumors, high mRNA expression of TNF, RIPK1 and STX37 are indicative of response." (PMID 33546280, 2021). "This suggests that enhancing the mitochondrial proteins and functions in MDA-MB-231 cells in the presence of TNF-α can inhibit the triple-negative breast cancer cell survival." (PMID 33926547, 2021). "Triple-negative breast cancer (TNBC) induced TDO2 mRNA in co-culture with TNF-α and IL-1β This increase is through NF-κβ activation." (PMID 32050636, 2020). "In addition, the responders of a neoadjuvant trial using LCL161 in triple-negative breast cancers exhibited high TNF-α and RIPK1 levels." (PMID 37867861, 2023). "In addition, TNFα contributes to the aggressive properties of triple-negative breast cancer cell lines via the upregulation of TNFAIP3(A20)." (PMID 32986377, 2020).